PYCR1 (pyrroline-5-carboxylate reductase 1)
Diseases named in the same sentence as PYCR1 in open-access papers (continued):
Sharing a sentence is not in itself a finding about the gene and the disease.
lung adenocarcinoma (continued). "Therefore, we speculated that PYCR1 enhanced the invasion of lung adenocarcinoma cells and this might be related to its enhancement of glycolysis and lactic acid production in tumor cells." (PMID 31143549, 2019). "Thus, we speculated that the PYCR1 gene might be related to the specific physiological characteristics of lung adenocarcinoma." (PMID 31143549, 2019). "Furthermore, PYCR1 plays a critical role in resistance of lung adenocarcinoma to cisplatin, which might be a potential therapeutic target for lung adenocarcinoma, thereby providing theoretical data for the chemotherapy of the disease." (PMID 31143549, 2019). "Lung adenocarcinoma NCI-H1299 and A549 cells in PYCR1-silencing/vector control/blank control groups were cultured for 24 h, and then cell proliferation in each group was measured using CCK8 reagent for five consecutive days." (PMID 31143549, 2019). "Lung adenocarcinoma NCI-H1299 and A549 cells in PYCR1-silenced/vector control/blank control groups were treated with different concentrations of cisplatin, and the rate of inhibition on the proliferation was detected using the CCK8 assay." (PMID 31143549, 2019). "Lung adenocarcinoma NCI-H1299 and A549 cells in PYCR1-silencing/vector control/blank control groups were inoculated on 96-well plate, respectively." (PMID 31143549, 2019). "Lung adenocarcinoma NCI-H1299 and A549 cells in PYCR1-silencing/vector control/blank control groups were inoculated into the upper chamber of Transwell chamber." (PMID 31143549, 2019). "Knockout of PINCH1 in lung adenocarcinoma cells resulted in increased DRP1 expression and therefore mitochondria fission, which led to a reduction in the level of pyrroline-5-carboxylate reductase 1 (PYCR1), an essential enzyme in proline synthesis, therefore reducing proline synthesis." (PMID 35326584, 2022). "Finally, ablation of PINCH-1 from lung adenocarcinoma in mouse increases DRP1 expression and inhibits PYCR1 expression, proline synthesis, fibrosis and tumor growth." (PMID 33004813, 2020). "Of note, knockdown of DRP1 in PINCH-1 KO lung adenocarcinoma cells, but not that in PINCH-1 expressing wild type lung adenocarcinoma cells, significantly increased the level of PYCR1 and proline synthesis." (PMID 33004813, 2020). "Finally, we provide in vivo evidence showing that ablation of PINCH-1 from lung adenocarcinoma in mouse increases DRP1 expression and reduces the levels of PYCR1, proline synthesis, collagen matrix, and tumor growth." (PMID 33004813, 2020). "To test whether PINCH-1 regulates DRP1, PYCR1, proline synthesis, and tumor growth in vivo, we ablated PINCH-1 from KrasG12D-induced lung adenocarcinoma in mice, which normally expressed a high level of PINCH-1." (PMID 33004813, 2020). "Consistent with the results from cultured lung adenocarcinoma cells, ablation of PINCH-1 from lung adenocarcinoma significantly increased the protein and mRNA levels of DRP1 and reduced the levels of PYCR1 and proline in vivo." (PMID 33004813, 2020). "The cell migration was detected by the scratch test, and the silencing of the PYCR1 gene did not affect the migration of lung adenocarcinoma cells significantly." (PMID 31143549, 2019). "Although some studies explored the role of PYCR1 in the proliferation of human lung squamous cell carcinoma H1703 cells and human lung adenocarcinoma SPC-A1 cells, the correlation of PYCR1 gene with cell migration, invasion, and cisplatin sensitivity in lung adenocarcinoma was not examined." (PMID 31143549, 2019).
lung carcinoma (13 papers, 2019 to 2025). "Collectively, our results demonstrate that PYCR1 is a key regulator of lung cancer progression and is functionally linked to both EGFR and TLR signaling pathways." (PMID 41254241, 2025). "Recent studies have implicated pyrroline-5-carboxylate reductase 1 (PYCR1), a key enzyme in proline biosynthesis, in cancer progression, yet its specific role in lung cancer remains unclear." (PMID 41254241, 2025). "To verify the functional role of PYCR1 in lung cancer, we generated PYCR1-knockout (PYCR1-KO) human lung cancer cells using CRISPR–CRISPR-associated protein 9 (Cas9) gene editing to assess the impact of PYCR1 loss on cell proliferation, migration and tumor formation in both in vitro and in vivo." (PMID 41254241, 2025). "Furthermore, gene sets related to NSCLC and broader cancer-related pathways were remarkably enriched in patients with PYCR1up NSCLC, providing strong evidence for the association between elevated PYCR1 expression and lung cancer progression." (PMID 41254241, 2025). "Importantly, elevated PYCR1 expression has been associated with various cancers, but its role in lung cancer progression and signaling networks remains largely unexplored." (PMID 41254241, 2025). "To validate the functional role of PYCR1 in lung cancer, we generated PYCR1-KO human lung cancer cell lines using CRISPR–Cas9 gene editing." (PMID 41254241, 2025). "We observed that the migratory ability of lung cancer cells, assessed using wound-healing and Transwell assays, was significantly reduced in PYCR1-KO A549 and PYCR1-KO H1299 cells treated with EGF or TLR agonists compared with Ctrl cells." (PMID 41254241, 2025). "Having established the role of PYCR1 in lung cancer progression, we investigated its potential as a therapeutic target against EGFR- and TLR-induced tumor formation." (PMID 41254241, 2025). "The therapeutic inhibition of PYCR1, particularly using PYCR1-IN-1, highlights a promising strategy for targeting lung cancer driven by hyperactive EGFR and TLR signaling." (PMID 41254241, 2025). "Upregulated PYCR1 expression has been demonstrated to activate STAT3 phosphorylation in lung cancer, which in turn leads to elevated PD-L1 expression and subsequent inhibition of T cell infiltration." (PMID 40598593, 2025). "Pyrroline-5-carboxylic acid reductase 1 (PYCR1) has been identified as a key player in the progression of lung cancer, functioning through a metabolic linkage between proline and glutamine." (PMID 40598593, 2025). "Functional studies in PYCR1-knockout (PYCR1-KO) lung cancer cells generated via CRISPR–Cas9 showed reduced cell proliferation, migration, colony formation and tumor spheroid growth both in vitro and in vivo." (PMID 41254241, 2025). "This study underscores the pivotal role of PYCR1 in driving lung cancer progression through its involvement in EGFR and TLR signaling pathways—two key regulators of tumor proliferation, migration and metastasis." (PMID 41254241, 2025). "WT A549 and WT H1299 lung cancer cells were treated with PYCR1-IN-1 at concentrations ranging from 3 μM to 81 μM." (PMID 41254241, 2025). "Functionally, PYCR1-KO lung cancer cells showed a significant reduction in cancer progression in response to EGF stimulation." (PMID 41254241, 2025). "Based on these results, we examined the effects of PYCR1-IN-1 at a concentration of 10 μM, which induced approximately 20% cytotoxicity in lung cancer cells." (PMID 41254241, 2025). "Consistently, cell proliferation was markedly reduced in PYCR1-KO A549 and PYCR1-KO H1299 cells, indicating that PYCR1 supports the proliferation and migration of lung cancer cells." (PMID 41254241, 2025). "PYCR1 is a key mitochondrial enzyme that facilitates the last step in glutamine-to-proline conversion, and its overexpression of PYCR1 is involved in the progression of several cancers, including breast and lung cancer." (PMID 37046716, 2023).
lung carcinoma (continued). "Consistent with the studies in lung cancer cells in culture, the levels of PYCR1 and proline were significantly reduced in response to conditional KO of kindlin-2, confirming that kindlin-2 is critical for control of PYCR1 and proline levels in vivo." (PMID 30783087, 2019). "To this end, we utilized PYCR1-IN-1, a chemical inhibitor of PYCR1, and conducted preliminary assessments of its effectiveness in reducing the growth of 3D tumor spheroids derived from lung cancer cells to determine the optimal concentration." (PMID 41254241, 2025). "The study concludes that PYCR1 is important for lung cancer progression and could be a target for new treatments." (PMID 41254241, 2025). "To test this hypothesis, we analyzed PYCR1 expression levels in lung cancer tissues using the Gene Expression Profiling Interactive Analysis (GEPIA) database and confirmed our findings with cohort microarray datasets from 42 patients with NSCLC." (PMID 41254241, 2025). "Given the potential interplay between PYCR1 and these signaling pathways, we hypothesized that PYCR1 might be functionally associated with EGFR and TLR signaling in lung cancer." (PMID 41254241, 2025). "Moreover, FERMT2 has been confirmed to function as a mechanosensor in human lung cancer tissues, where it interacts with the proline synthesis enzyme PYCR1 in response to alterations in ECM stiffness." (PMID 40119586, 2025). "Importantly, we provide molecular and cellular evidence demonstrating that PYCR1 is functionally implicated in EGFR- and TLR-driven lung cancer progression, highlighting its potential as both a biomarker and a therapeutic target for lung cancer." (PMID 41254241, 2025). "An interesting interplay between proline metabolism/collagen synthesis and microenvironment stress was reported in a recent study on lung cancer, in which the authors show the interaction of PYCR1 in the mitochondria with Kindlin-2, a protein critical for integrin-mediated cell-ECM adhesion." (PMID 34769188, 2021). "For example, PYCR1 may be a novel therapeutic target for inhibiting cell proliferation in lung cancer." (PMID 31992202, 2020). "Since PYCR1 was found to be negatively regulated by miR-488, which is related to cell proliferation and tumorigenesis, it was reported to be a novel therapeutic target in lung cancer." (PMID 31739630, 2019). "Collectively, our findings establish PYCR1 as a critical regulator of EGFR and TLR signaling pathways, driving lung cancer progression." (PMID 41254241, 2025). "Functionally, we observed that lung cancer cell migration, proliferation, colony formation and 3D tumor spheroid formation induced by TLR agonists were markedly attenuated following PYCR1 depletion." (PMID 41254241, 2025). "In an experiment on lung cancer cells (with high MYC expression), the effects of MYC knockdown and the enzymes under the control of MYC, PYCR1/2/L, and P5CS, were investigated." (PMID 34769188, 2021). "Experiments on lung cancer cell lines have shown that the addition of P5C and increased expression of MYC through up-regulation of the enzymes P5CS, PYCR1, PYCR2, PYCRL increases glycolysis." (PMID 34769188, 2021). "Recent studies have identified the enzyme pyrroline-5-carboxylate reductase 1 (PYCR1) as a potential contributor to cancer progression, but its specific role and underlying mechanisms in lung cancer have not been fully elucidated." (PMID 41254241, 2025). "Importantly, treatment with PYCR1-IN-1, a selective PYCR1 inhibitor, significantly suppressed EGFR- and TLR-induced tumor spheroid growth in multiple lung cancer cell lines, underscoring PYCR1’s potential as a therapeutic target." (PMID 41254241, 2025). "Given the established role of PYCR1 in regulating EGFR- and TLR-mediated signaling, we investigated whether PYCR1 influences lung cancer progression in response to EGF and TLR agonists." (PMID 41254241, 2025).
lung carcinoma (continued). "Researchers have found that an enzyme called pyrroline-5-carboxylate reductase 1 (PYCR1) might play a role in cancer growth, but its exact function in lung cancer is unclear." (PMID 41254241, 2025).
colorectal cancer (11 papers, 2020 to 2025). A primary or metastatic malignant neoplasm that affects the colon or rectum. "In colorectal cancer cells, PYCR1 knockdown is associated with reduced activity of the MAPK pathway and NF-kB signaling, phenotypes that seem to depend on signal transducer and activator of transcription (STAT) 3-mediated signaling." (PMID 33083024, 2020). "Functionally, PYCR1 Tyr-135 phosphorylation exerts supportive effect on tumor growth under hypoxia, and the level of PYCR1 Tyr-135 phosphorylation is associated with malignancy of colorectal cancer (CRC)." (PMID 37777542, 2023). "PYCR1 has also been reported as a target gene for 5-fluorouracil-induced ferroptosis and apoptosis in colorectal cancer, and its overexpression can confer resistance to 5-fluorouracil-induced cytotoxic effects in colorectal cancer cells." (PMID 40430095, 2025). "Then, the clinical relevance of PYCR1 pY135 was further evaluated in 150 colorectal cancer patient samples." (PMID 37777542, 2023). "First, PYCR1 knockdown has been shown to inhibit proliferation, drug resistance and EMT by affecting the STAT3-mediated p38 MAPK and NF-κB pathways in colorectal cancer cells." (PMID 41254241, 2025). "In colorectal cancer (CRC), PYCR1 is phosphorylated at Tyr‐135 by nuclear IGF1R under hypoxia, which promotes its binding to ELK4 and recruitment to gene promoters." (PMID 39422696, 2024). "Here, the authors show nuclear localized PYCR1 undergoes IGF1R-mediated phosphorylation under hypoxia, binds with ELK4 and recruits SIRT7 to modulate transcription of target genes to promote colorectal cancer progression." (PMID 37777542, 2023). "PYCR1 facilitated cell growth, drug resistance and EMT through activating p38 MAPK and NF-kappaB signaling pathways of colorectal cancer cells." (PMID 34696668, 2021). "Furthermore, silencing of PYCR1 reduces the cell growth, drug resistance, and epithelial-mesenchymal transition (EMT) by inactivating the p38 mitogen-activated protein kinase (MAPK) and NF-κB signaling pathways in colorectal cancer cells." (PMID 34696668, 2021).
melanoma (11 papers, 2012 to 2024). A malignant, usually aggressive tumor composed of atypical, neoplastic melanocytes. "In melanoma cells, knockdown of PYCR1 causes decreased activity of the Akt pathway and reduces the expression of RAPTOR, suggesting a downstream inhibition of protein synthesis." (PMID 33083024, 2020). "Previously, PYCR1 knockdown has been shown to reduce p-mTOR in renal cell carcinoma and p70 in melanoma." (PMID 35105345, 2022). "Moreover, ALDH18A1 knock-down activates AAR stress signaling, and reduces melanoma tumor growth both in vitro and in vivo, whereas PYCR1 induction improves proliferation and invasiveness of breast, esophagus, lung, melanoma, pancreas, and prostate cancer cells." (PMID 34458276, 2021). "We found that DTIC significantly affected the expression levels of various metabolic enzymes, including ADSL, PYCR1, PRODH, and FTH1, in melanoma cells." (PMID 37976135, 2023). "Three enzymes involved in the biosynthetic route from glutamate to proline (P5CS, PYCR1 and PYCR2) are up-regulated in melanoma compared to melanocytes." (PMID 23024808, 2012). "Moreover, isotope enrichment experiments in melanoma cell lines showed that PYCR1 and PYCR2 primarily catalyze the synthesis of L-proline from glutamate, although, in the presence of high levels of ornithine, PYCR1 can also produce L-proline through ornithine." (PMID 33083024, 2020). "PYCR1 and PYCR2 are abundant in melanoma cells but not detected in melanocytes." (PMID 23024808, 2012).
glioma (9 papers, 2018 to 2025). A benign or malignant brain and spinal cord tumor that arises from glial cells (astrocytes, oligodendrocytes, ependymal cells). "We further investigated PYCR1 expression in IDH1 WT and mutated gliomas and confirmed that tumors with high 2HG concentrations (for examples) also demonstrated increased expression of PYCR1." (PMID 29562167, 2018). "However, collectively, the in vitro and in vivo data, therefore, suggest that PYCR1 may play a role in redox regulation in IDH1-mutated gliomas." (PMID 29562167, 2018). "Through comprehensive investigation of the regulation of central carbon metabolism, we are able to show that glioma cells expressing mutant IDH1 increase the synthesis of proline through the activity of PYCR1, a mitochondrial NADH-oxidising enzyme." (PMID 29562167, 2018). "Proline biosynthesis is documented to support redox homeostasis in IDH1-mutant glioma by reducing the NADH/NAD + ratio via PYCR1 activity, which enables continuation of TCA cycle activity when flux through the electron transport chain is limiting as seen in hypoxic conditions." (PMID 39816516, 2025). "Interestingly, to produce proline via PYCR1, glutamate-derived P5C is primarily used; therefore, cellular glutamate, known for its influence both on glia and glioma cells, is depleted." (PMID 38275897, 2024). "For instance, PYCR1 could cooperate with isocitrate dehydrogenase 1 (IDH1) to promote cancer cell survival in glioma and esophageal squamous cell cancer." (PMID 31428683, 2019). "To determine whether the same phenotype was observable in vivo, we first investigated the expression of PYCR1 and PYCR2 in low-grade gliomas, in which IDH1 mutations are commonly observed." (PMID 29562167, 2018). "Furthermore, we found that IDH1 mutant gliomas exhibit increased PYCR1 expression and that tumoral 2HG concentrations correlated with that of proline, suggesting that this effect is also observed in glioma patients." (PMID 29562167, 2018). "Therefore, although our results indicate significant differences only in the PYCR1 isoform, it would seem appropriate to refrain from definite conclusions dismissing the role of PYCR2 and PYCR3 in gliomas until the wider context of the multi-layered metabolic network involved is better understood." (PMID 38275897, 2024).
non-small cell lung carcinoma (9 papers, 2020 to 2025). A group of at least three distinct histological types of lung cancer, including non-small cell squamous cell carcinoma, adenocarcinoma, and large cell carcinoma. "Independent studies bring to the findings that PYCR1 is overexpressed also in non-small cell lung cancer (NSCLC) and has been associated with poor prognosis in patients with NSCLC." (PMID 32500033, 2020). "The researchers used data from 42 patients with non-small-cell lung cancer to study PYCR1 levels in cancer tissues." (PMID 41254241, 2025). "Another study confirmed that PYCR1 was negatively regulated by miR-488 and promoted the occurrence and development of non-small cell lung cancer by activating the p38mapk pathway." (PMID 35371311, 2022). "PYCR1 was also reported to promote proliferation and inhibit apoptosis in non-small cell lung cancer." (PMID 33461172, 2021). "For example, PYCR1 was downregulated by miR-488, which promoted cell proliferation and inhibited cell apoptosis, and activated the p38/MAPK pathway in non-small-cell lung cancer (NSCLC)." (PMID 35293266, 2022).
cutis laxa (8 papers, 2015 to 2022). Cutis laxa (CL) is an inherited or acquired connective tissue disorder characterized by wrinkled, redundant and sagging inelastic skin associated with skeletal and developmental anomalies and, in some cases, with severe systemic involvement. "Fibroblasts deficient in PYCR1, derived from patients with cutis laxa, showed increased sensitivity to oxidative stress." (PMID 26733354, 2016). "Clinical data pointed out that homozygotic or heterozygotic mutation in the pyrroline-5-carboxylate reductase 1 (PYCR1) gene in humans caused cutis laxa (ARCL) disease, with progeroid appearance, lax and wrinkled skin, joint laxity, osteopenia, and mental retardation phenotypes." (PMID 31091804, 2019). "Homozygous mutations in ALDH18A1 (or other genes e. g., PYCR1, ATP6V0A2) can result in a heteogenous group of rare diseases characterized by loose or wrinkly skin known as cutis laxa." (PMID 26569114, 2015). "Unlike the patients with PYCR1 deficiency, the PYCR2-deficient patients did not have cutis laxa or osteopenia." (PMID 28990419, 2019).